OAS3 (2'-5'-oligoadenylate synthetase 3)
Diseases named in the same sentence as OAS3 in open-access papers (continued):
Sharing a sentence is not in itself a finding about the gene and the disease.
dermatomyositis (4 papers, 2023 to 2026). Dermatomyositis (DM) is a type of idiopathic inflammatory myopathy characterized by evocative skin lesions and symmetrical proximal muscle weakness. "As a result, M2 macrophages were positively associated with the expression of IFIT3, OAS3, ISG15, and RSAD2 in patients with inflammatory cardiomyopathy and dermatomyositis, respectively." (PMID 37118825, 2023). "In one study, ISG15, IFIT3, OAS3, and RSAD2 were prominently enriched in the type I IFN signaling pathway, serving as central hub genes associated with myocarditis-related immune processes, suggesting their potential involvement in the mechanism of myocardial injury in dermatomyositis." (PMID 38753730, 2024). "This miRNA appears to regulate genes enriched in type I interferon signaling pathways (IFIT3, OAS3, ISG15, and RSAD2), which correlate with increased M2 macrophage infiltration in both dermatomyositis and myocarditis." (PMID 40433545, 2025).
HIV-1 infection (4 papers, 2019 to 2023). The type species of lentivirus and the etiologic agent of acquired immunodeficiency syndrome (AIDS). "HIV-1 infection of pericytes significantly upregulated expression of all OAS genes at the mRNA level but selectively OAS1, OAS2 and OAS3 at the protein level." (PMID 36778388, 2023). "Most interestingly, silencing of OAS1, OAS2, OAS3, or OASL markedly increased HIV-1 replication in human brain pericytes, providing the first evidence that the OAS family can regulate HIV-1 infection in human pericytes." (PMID 37209263, 2023). "There was a significant increase in the expression of OAS2 and OAS3 proteins 24, 48, or 72 h post HIV-1 infection; however, these changes were more prominent for OAS 2 than those for OAS3." (PMID 37209263, 2023). "In addition, significant changes were observed in the expression of coding genes involved in the host response to infection (e.g., ISG15, STAT1, OAS3, ISG20, CCL2, and MX1), confirming robust HIV-1 infection of these cells." (PMID 31551335, 2019).
ZIKV infection (4 papers, 2018 to 2025). "At 36 h post-ZIKV infection, the expression levels of interferon-induced antiviral proteins, including ISG15, ISG56, OAS1, OAS2, and OAS3, were increased by TRIM38 overexpression and decreased by TRIM38 knockout." (PMID 40006954, 2025). "We also found that ZIKV infection induced the expression of OAS2, as well as OAS1 and OAS3 in A549 cells." (PMID 32276512, 2020). "During ZIKV infection in this individual, there was similar strong induction of type I ISGs, exemplified by MX1, OAS3, RSAD2, and IFI27 genes (Cluster 2), but minimal coincident induction of chemokines involved in leukocyte chemotaxis (Cluster 1)." (PMID 30596671, 2018).
gastric cancer (3 papers, 2020 to 2024). A primary or metastatic malignant neoplasm involving the stomach. "In trastuzumab-resistant gastric cancer, OAS1, OAS2, OAS3, and OASL were all identified as key genes." (PMID 38380081, 2024). "OAS1, OAS2, OAS3, and OASL have been recognised as pivotal genes in a bioinformatic study focusing on trastuzumab-resistant gastric cancer." (PMID 36567857, 2022). "Our previous research indicated that OAS1, OAS2, OAS3 and OASL were all identified as hub genes from the protein-protein interaction network of differentially expressed genes between the trastuzumab-resistant gastric cancer and control groups." (PMID 32560641, 2020).
lung adenocarcinoma (3 papers, 2020 to 2022). A carcinoma that arises from the lung and is characterized by the presence of malignant glandular epithelial cells. "In lung adenocarcinoma (LUAD), IFN-γ response genes, TRAFD1 is reported to exhibit significant expression and a strong positive correlation with OAS3." (PMID 36672782, 2022). "A previous study showed that lung adenocarcinoma (A549) cells constitutively expressed OAS1 and OAS3 mRNA." (PMID 34099596, 2021).
measles (3 papers, 2022 to 2025). A highly contagious viral infection caused by the measles virus. "In the cases of RNA viruses, including influenza A, measles, and coronavirus disease, downregulation of genes such as Ddx58, Il1b, Stat1, Stat2, Oas3, Oas2, Oas1a, Oas1g contributes to increased susceptibility to infections." (PMID 40206211, 2025).
myocarditis (3 papers, 2023 to 2025). Myocarditis is a condition that is characterized by inflammation of the heart muscle (myocardium). "We found M2 macrophages increased in DM and myocarditis compared to the healthy control, associating with the expression of IFIT3, OAS3, ISG15, and RSAD2 in DM and myocarditis positively." (PMID 37118825, 2023). "The expression levels of IFIT3, OAS3, ISG15, and RSAD2 were verified in myocardial tissue between myocarditis mice and normal control." (PMID 37118825, 2023). "We finally identified 4 common hub-genes related to the immune process of myocarditis and DM: IFIT3, OAS3, ISG15, and RSAD2." (PMID 37118825, 2023).
Sepsis (3 papers, 2019 to 2025). Sepsis is defined as life-threatening organ dysfunction caused by a dysregulated host response to infection. "For the first time, we identified TRIM21 as the E3 ligase accounting for OAS3 K48-linked polyubiquitination at the K1079 site and its dowregulation in the sepsis model led to a decrease in the OAS3 ubiquitination level and an increase in the OAS3 protein level in lung epithelial cells." (PMID 39494334, 2024). "Next, we explored whether OAS3 upregulation is responsible for sepsis-induced acute lung injury (SALI) with lung epithelial cells-specifically expressed AAV9-shOAS3 (inserted with the SFTPC promoter element) intratracheally injected into the mouse lung." (PMID 39494334, 2024). "In this study, we indicated that OAS3 protein increases in a proteasomal-dependent way and OAS3 K48-linked polyubiquitination decreases due to the E3 ligase TRIM21 downregulation in the sepsis model, which is consistent with the traditional degradative function of K48-linked chains." (PMID 39494334, 2024). "Notably, overexpression of TRIM21 in MLE12 cells or mice reversed the sepsis-induced increase in OAS3 protein level." (PMID 39494334, 2024). "In order to determine whether OAS3 could functionally influence sepsis-induced lung epithelial cell apoptosis, we analyzed the apoptosis levels in vivo and in vitro by TUNEL staining." (PMID 39494334, 2024). "The upregulated OAS3 promotes epithelial cell apoptosis through its downstream effector molecule, RNase L. These findings offer a novel perspective for further understanding the progression of sepsis and identifying potential therapeutic targets for its treatment." (PMID 39494334, 2024). "In addition, the deubiquitination of OAS3 due to the downregulation of the E3 ligase TRIM21 promotes epithelial cell apoptosis and drives sepsis-induced acute lung injury." (PMID 40170095, 2025). "In this study, we identified OAS3 as a possible candidate resulting in sepsis-induced acute lung injury (SALI) through multi-omics analysis and confirmed its role as a promoter for SALI and epithelial cell apoptosis in the sepsis model." (PMID 39494334, 2024). "Furthermore, OAS3 overexpression-induced apoptotic cell number significantly decreased after inhibition of RNase L with EA and Myr in MLE12 cells under LPS stimulation in vitro or in mice under CLP operation in vivo, suggesting that OAS3 aggravates cell apoptosis via RNase L in sepsis." (PMID 39494334, 2024). "We identified 687 differentially expressed genes between ARDS and ARDS-HSCT (adjusted p-value < 0.01), including IFI44L, OAS3, LY6E, and SPATS2L that had increased expression in ARDS vs. ARDS-HSCT; these genes were not differentially expressed in sepsis vs sepsis-HSCT." (PMID 30665420, 2019).
tuberculosis (3 papers, 2022 to 2024). A chronic, recurrent infection caused by the bacterium Mycobacterium tuberculosis. "Therefore, the increase in levels of OAS3 protein in the presence of cryptolepine supports the ethnopharmacological use of C. sanguinolenta in the management of tuberculosis." (PMID 35928633, 2022). "The 2′,5′-oligoadenylate synthetase (OAS) family, including OAS1, OAS2, and OAS3, is composed of IFN-induced antiviral enzymes and has been well studied in the field of tuberculosis." (PMID 36567857, 2022).
AIDS (2 papers, 2016 to 2019). A syndrome resulting from the acquired deficiency of cellular immunity caused by the human immunodeficiency virus (HIV). "Additionally, SNPs that associated with progression from HIV infection to AIDS were identified in two 2′-5′-oligoadenylate synthetase genes (OAS2 and OAS3)." (PMID 28050553, 2016). "Additionally, novel SNPs that associated with progression from HIV infection to AIDS were identified in OAS2 and OAS3 genes." (PMID 28050553, 2016).
epilepsy (2 papers, 2021 to 2022). A brain disorder characterized by episodes of abnormally increased neuronal discharge resulting in transient episodes of sensory or motor neurological dysfunction, or psychic dysfunction. "Interestingly, we observed that when compared to the normal controls, the expression of some identified genes was only significantly altered either in Epilepsy (EGLN1, ELAVL4, and NFE2l2) or Hemorrhage (USP22, EYA1, SIX1, OAS3, SRMS) groups." (PMID 34588521, 2021).
Hepatitis (2 papers, 2022 to 2024). Inflammation of the liver. "ISGs that were more highly expressed in hepatocytes in the HBeAg‐positive infection phase than in the hepatitis phases, including IFI44, ISG15, IFI44L, MX1, and OAS3, were not correlated with ALT levels." (PMID 39135698, 2024).
Herpes simplex infection (2 papers, 2022). "After treatment of a metastatic BC patient with herpes simplex infection pathway (associated KGs: OAS1, OAS3, ATF6B, IRF9), there has created a case of Sweet Syndrome." (PMID 35617355, 2022). "The KEGG pathway analysis highlighted that a large number of genes that were up-regulated after infection with V2 were the same as those upregulated in response to Herpes simplex infection (genes Myd88, Irf7, H2-Q7, Casp8, Tlr3, Daxx, C3, H2-Aa, Oas2, Oas3, H2-T22, H2-T23 and Cd74)." (PMID 35458422, 2022).
Obesity (2 papers, 2022 to 2024). Accumulation of substantial excess body fat. "A novel finding of the current study is the upregulation of OAS2 and OAS3, genes that encode oligoadenylate synthetases that synthesize 2′-5′-linked oligoadenylates, in individuals living with obesity." (PMID 35247847, 2022).
ovarian carcinoma (2 papers, 2018 to 2021). A malignant neoplasm originating from the surface ovarian epithelium. "To further confirm TAG72 as an ovarian cancer CAR target and the anti-tumor activity of our TAG72-BBζ CAR T cells, we performed in vitro assays utilizing human ovarian cancer ascites from three patients (OAS3, OAS4, OAS7)." (PMID 30510550, 2018).
pancreatic cancer (2 papers, 2022). "OAS3 stains exhibited weak intensity in normal pancreatic tissues but showed medial intensity in pancreatic cancer tissues." (PMID 35719943, 2022). "Results derived from these three databases all indicated that elevated levels of OAS1, OAS2, OAS3, and OASL were associated with poor overall survival (OS) in pancreatic cancer." (PMID 35719943, 2022). "ASPM, CCNB1, CDK1, MELK, OAS3, PPTG1 and TOP2A were thought to be significantly associated with shorter overall survival in pancreatic cancer patients." (PMID 36167975, 2022). "In Pei Pancreas dataset, OAS3 was 6.317 times higher in pancreatic carcinoma compared to normal tissues, In Logsdon Pancreas dataset, OASL was 77.098 times higher in pancreatic adenocarcinoma compared to the normal pancreatic tissues." (PMID 35719943, 2022). "In Pei Pancreas dataset, OAS3 was 3.562 times higher in pancreatic carcinoma compared to normal pancreatic tissues." (PMID 35719943, 2022). "Western blotting results showed that the protein expression levels of OAS1, OAS2, OAS3, and OASL were significantly elevated in pancreatic cancer cells compared with normal pancreatic cells." (PMID 35719943, 2022). "The potential prognosis values of OAS1, OAS2, OAS3, and OASL in pancreatic cancer were investigated using Kaplan-Meier Plotter, GEPIA, and OncoLnc databases." (PMID 35719943, 2022). "We further analyzed the mRNA levels of OAS1, OAS2, OAS3, and OASL in pancreatic cancer tissues and normal pancreatic tissues based on Oncomine and GEPIA databases." (PMID 35719943, 2022). "The co-expressed genes that related to OAS1, OAS2, OAS3, and OASL were respectively identified in Pei Pancreas dataset of Oncomine database with 16 normal pancreatic tissues and 36 pancreatic carcinoma tissues." (PMID 35719943, 2022). "The expressions of OAS2 and OAS3 had significant negative correlations with tumor purity in pancreatic cancer (cor = −0.219 and −0.182, respectively, P < 0.05)." (PMID 35719943, 2022). "In addition, by analyzing the GEPIA database, the mRNA levels of OAS1, OAS2, OAS3, and OASL were all significantly higher in pancreatic cancer tissues than normal pancreatic tissues." (PMID 35719943, 2022). "Immunohistochemical stains of OAS1, OAS2, OAS3 and OASL proteins in human pancreatic cancer tissues and normal pancreatic tissues were searched from the HPA database." (PMID 35719943, 2022).
acute myeloid leukemia (1 paper, 2026). Acute myeloid leukemia (AML) is a group of neoplasms arising from precursor cells committed to the myeloid cell-line differentiation. "Finally, we found that OAS3 was observably related with some mutation types (CEBPA, FLT3 internal tandem duplication, NRAS, and EVI1 expression) in patients with acute myeloid leukemia (LAML)." (PMID 41700140, 2026).
allergic asthma (1 paper, 2022). A asthma with a basis in a pathological type I hypersensitivity reaction. "MX1, RSAD2, IFIT1, IFI27, OAS3, and SAMD9L were markedly elevated in HDM-treated mice and positively associated with IL-5, IL-13 and MUC5AC (key mediators of allergic asthma)." (PMID 36211429, 2022). "Furthermore, MX1, RSAD2, IFIT1, IFI27, OAS3, and SAMD9L levels correlated positively with IL-5, IL-13, and MUC5AC levels, which are the key mediators of allergic asthma." (PMID 36211429, 2022).
Aortic Rupture (1 paper, 2022). The tearing or bursting of the wall along any portion of the AORTA, such as thoracic or abdominal. "OAS3, IFIT1, and IFI44L may be predictive factors for aortic rupture." (PMID 36158807, 2022).
Arthritis (1 paper, 2020). Inflammation of a joint. "Active SLE patients with arthritis showed higher OAS2 and OAS3 expression in PBMCs and CD19+ B cells and OAS2 expression in CD4+ T cells (P<0.05)." (PMID 32321151, 2020). "Moreover, active SLE patients with renal disorders and arthritis showed higher OAS2, OAS3, and OASL expression than patients without these symptoms." (PMID 32321151, 2020).
atherosclerosis (1 paper, 2022). A disease characterized by the build-up of fatty material and calcium deposition in the arterial wall resulting in partial or complete occlusion of the arterial lumen. "IFIH1, IFIT1, IFIT2, IFIT3, ISG15 and OAS3 had similar expression differences to the training set and had good diagnostic abilities for atherosclerosis." (PMID 36437453, 2022). "Our study identified IFIH1, IFIT1, IFIT2, IFIT3, ISG15 and OAS3 as immune-related hub genes of atherosclerosis." (PMID 36437453, 2022).
bladder cancer (1 paper, 2022). "The TF-protein JUN (a regulator of ANGPT1, HPGD, ATF6B and OAS3) is associated with bladder cancer disease." (PMID 35617355, 2022).
bladder urothelial carcinoma (1 paper, 2022). "The genes co-expressed with OAS1, OAS2, OAS3, and OASL in Sanchez-Carbayo Bladder 2 dataset were identified using Oncomine in 48 normal samples, 81 filtrating bladder urothelial carcinoma tissues, and 28 superficial bladder cancer tissues." (PMID 36162993, 2022).
breast tumors (1 paper, 2024). "Taken together, these findings underscore the distinct expression patterns of OAS1, OAS2, OAS3, and OASL in breast tumors across a spectrum of immune and molecular subtypes." (PMID 39633486, 2024).
bronchiolitis (1 paper, 2023). Inflammation of the bronchioles characterized by swelling of the bronchioles and mucus accumulation. "IFI27, together with other genes that were differentially expressed, such as IFI44, OAS3, EPSTII, and IFI44L, are generally significantly up-regulated in whole blood from infants admitted to hospital with severe RSV-bronchiolitis." (PMID 36622786, 2023).
chronic lymphocytic leukemia (1 paper, 2022). "At present, only a few studies showed that OAS3 affects the occurrence and development of chronic lymphocytic leukemia." (PMID 36162993, 2022).
colitis (1 paper, 2017). Inflammation of the colon. "After induction of acute colitis with DSS, we found with EdgeR and CuffDiff2 analyses that the expression of 11 genes (Clps, Ddx60, Fgb, Fgg, Ifi44, Ifit2, Isg15, Itih3, Itih4, Oas3 and Usp18), which are involved in antimicrobial response, was increased in MMP-9−/− compared to WT mice." (PMID 28561062, 2017).
dependence (1 paper, 2023). "Two additional genes, OAS3 (2’-5’-Oligoadenylate Synthetase 3) and OXTR (Oxytocin Receptor) show evidence in the NHGRI GWAS catalog for association with alcohol consumption and dependence, respectively." (PMID 37217680, 2023).
disorders of sex development (1 paper, 2022). "DMRT3 and OAS3 are involved in human disorders of sex development (DSD) through the control of the ESR1 expression." (PMID 36551704, 2022).
Flavivirus Infections (1 paper, 2020). Infections with viruses of the genus FLAVIVIRUS, family FLAVIVIRIDAE. "The 2′,5′-oligoadenylate synthase (OAS) and RNase L pathways have previously been shown to restrict flavivirus infection, yet in ZIKVPR-infected SH-SY5Y cells, we observed that OAS3 was downregulated, while OASL was notably upregulated." (PMID 32380717, 2020).
glioma (1 paper, 2022). A benign or malignant brain and spinal cord tumor that arises from glial cells (astrocytes, oligodendrocytes, ependymal cells). "For example, OAS3 and MMP19 displayed higher expression levels in glioma samples compared to normal samples, recurrence samples compared to primary samples, high-risk group compared to low-risk group." (PMID 35729639, 2022).
Hypertension (1 paper, 2023). The presence of chronic increased pressure in the systemic arterial system. "Logistic regression analysis under five genetic models adjusted for age, sex, smoking history, DM, hypertension, and CAD was used to investigate the role of IFNAR2 rs2236757 and OAS3 rs10735079 polymorphisms in the susceptibility of COVID-19 infection and severity." (PMID 37745867, 2023).
infiltrating bladder urothelial carcinoma (1 paper, 2022). An invasive transitional cell carcinoma that arises from the urinary bladder urothelium. "In the Dyrskjot bladder 3 dataset, OAS3 was 1.567 times higher in infiltrating bladder urothelial carcinoma and was 1.380 times higher in superficial bladder cancer than in the respective normal tissues." (PMID 36162993, 2022). "OAS3 was also upregulated in infiltrating bladder urothelial carcinoma and superficial bladder cancer with a fold change respectively of 2.284 and 3.675 in the Sanchez-Carbayo bladder 2 dataset." (PMID 36162993, 2022).
lung carcinoma (1 paper, 2017). "Our microarray data analysis revealed and RT-qPCR confirmed the increased mRNA expression of all of the OAS gene family members (OAS1, OAS2, OAS3, OASL) and XAF1 and IRF7 in the lung cancer cell line A549 after transfection with BNC2." (PMID 28184177, 2017).
lupus nephritis (1 paper, 2023). Glomerulonephritis in the context of systemic lupus erythematosus. "Moreover, OAS1, OAS2, and OAS3 were closely related to lupus nephritis (LN) progression." (PMID 36655136, 2023).
malaria (1 paper, 2018). Malaria is a serious and sometimes fatal disease caused by a parasite that commonly infects a certain type of mosquito which feeds on humans. "The immunity related genes that are down-regulated in the malaria severity signature are: PRF1, GNLY, OAS2, MX1, OAS3 and CCL5." (PMID 29642892, 2018).